HIF1A (hypoxia inducible factor 1 subunit alpha)
Diseases named in the same sentence as HIF1A in open-access papers (continued):
Sharing a sentence is not in itself a finding about the gene and the disease.
cancer (continued). "Mechanistically, ASH1L co-opts with HIF-1α to induce a pro-metastatic transcriptome in cancer cells via catalyzing histone methylations at H3K4 and H3K36." (PMID 40394007, 2025). "Collectively, these data strongly indicate that the pseudohypoxic conditions generated by the reciprocal regulatory loop between HIF1α and CypD are crucial for cancer metastasis." (PMID 40701956, 2025). "The following section systematically summarizes the key molecular mechanisms through which HIF-1α contributes to cancer progression." (PMID 41311849, 2025). "Concerning resistance to apoptosis, HIF-1α acts to inhibit apoptotic pathways, promoting the adaptive survival of cancer cells." (PMID 40305214, 2025). "In conclusion, our comprehensive characterization of the immune microenvironment in multiple sites of OC reveals a subset of PLIN2hi macrophages that are enriched in ascites and promote ascitic development and cancer metastasis through HIF1α/SPP1 signaling." (PMID 39921309, 2025). "In contrast, glycerophospholipid metabolism and choline metabolism in cancer cells were significantly activated, leading to increased choline consumption and phosphatidylcholine accumulation, which correlated with elevated HIF‐1α levels." (PMID 40587842, 2025). "The high lactate availability in cancer drives lactylation of TFs, like HIF-1α, orchestrating tumor angiogenesis." (PMID 40651947, 2025). "HIF‐1α inhibitors, evaluated both as monotherapy and in combination with other agents, have shown potential in treating advanced or refractory cancers." (PMID 40954549, 2025). "Except for the canonical VHL-mediated rapid proteasomal degradation under normoxia, numerous novel regulators of HIF-1α are being identified, particularly in the context of cancer." (PMID 40164945, 2025). "In cancer, angiogenesis is often initiated by the overexpression of HIF-1α from hypoxic cancer cells in dormant or solid tumours." (PMID 40427172, 2025). "In GC, Quiescent cancer cells (QCCs) were found to promote the glycolytic reprogramming of M2 macrophages, which promoted hypoxia inducible factor 1 alpha (HIF1A)-mediated T-cell exhaustion and conferred cell resistance to ICIs." (PMID 40599798, 2025). "In the advanced phases of cancer progression, cancer cells induce oxidative stress, activating transcription factors HIF-1α and NF-κB." (PMID 40427390, 2025). "The activation of the Notch signaling pathway by HIF-1α in hypoxic environments plays a crucial role in preserving the stem-like characteristics of cancer stem cells." (PMID 40497987, 2025). "In this study, we reported that the ASH1L/HIF-1α complex in invading cancer cells promotes IGF-2 expression, which triggers AKT-GSK3b-mTOR signaling and activates OXPHOS pathways in monocytes in the bone niche." (PMID 40394007, 2025). "For this purpose, we performed experiments in a cobalt chloride (CoCl2)-modeled hypoxic environment and observed upregulation of HIF-1α at the protein level in almost all cancer cell lines used in the present study." (PMID 41514626, 2025). "Multiple previous studies have shown that HIF‐1α is involved in the regulation of many important steps of the metastatic processes of cancers." (PMID 40954549, 2025). "PI3K/Akt activate downstream mammalian target of rapamycin (mTOR) and HIF-1α, promoting angiogenesis, which is important for cancer cell survival in a hypoxic environment." (PMID 40427390, 2025). "Conversely, TSGA10 overexpression in certain cancers suppresses HIF-1α, inhibiting glycolysis and metastasis." (PMID 40507237, 2025). "The best-defined transcription factors regulating cancer cells’ response to hypoxia are HIF-1α and HIF-1β." (PMID 41226289, 2025). "CTGF, a direct transcriptional factor of HIF-1α, is a strong angiogenetic factor induced by hypoxia in several cancers." (PMID 40001578, 2025). "For instance, HIF-1α-mediated upregulation of glycolysis can enable cancer cells to survive in low-oxygen environments that would otherwise lead to cell death." (PMID 40901111, 2025).
cancer (continued). "The interplay between Cai2+ and HIF-1α and their positive feedback in cancer cells has been reviewed by Azimi." (PMID 40264757, 2025). "Activated under low-oxygen conditions, HIF-1α orchestrates a wide range of metabolic adaptations within cancer cells." (PMID 40322886, 2025). "For instance, the cooperative interaction between lncRNA and Ezh2 suppresses HIF-1α transcription, facilitating cancer cell adaptation to hypoxia." (PMID 40597665, 2025). "Our results indicated that VEGFA was secreted more than three-fold (p < 0.0001) in HIF1α over-expressed condition compared to wild type cancer cells, whereas after combinatorial treatment it was back to normal." (PMID 40045186, 2025). "Transcription factors like NF-κB, STAT3, and HIF-1α frequently exhibit abnormal activity, supporting cancer progression through enhanced survival, inflammation, and angiogenesis." (PMID 41311372, 2025). "In vitro, shikonin reduced the expression of PKM2, EGFR, PI3K, p-AKT, and HIF1α, which led to decreased viability of cancer cells, cell cycle arrest and apoptosis." (PMID 40076506, 2025). "By examining and evaluating the distinct prognostic associations across diverse malignancies and by highlighting the role of metabolic, ECM, and EMT pathways, we emphasize the potential of the WWOX/HIF1A ratio as a valuable biomarker for cancer prognosis." (PMID 41007296, 2025). "HIF-1α serves as a principal regulator of cellular responses to hypoxic conditions and has been thoroughly investigated for its role in cancer biology." (PMID 40136686, 2025). "It is believed that in many cancer-linked SDH mutations mitochondrial succinate accumulates in the cytoplasm and activates HIF-1α (hypoxia-inducible factor alpha), which favors pseudohypoxia-driven tumorigenesis through mal-activation of the target genes." (PMID 41155475, 2025). "Key regulators of cancer cell metabolism are hypoxia-inducible factor 1α (HIF-1α) and AMP-activated protein kinase (AMPK)." (PMID 39762846, 2025). "According to the Human Protein Atlas (HPA) database, HIF1α has the highest expression in CRC among different cancers." (PMID 40045186, 2025). "We show here, for the first time, that 2-ANPC interacts with HIF-1α and promotes its proteasome-mediated degradation, resulting in decreased HIF-1α expression in cancer cells both in vitro and in vivo." (PMID 41514626, 2025). "HIF-1α upregulates a wide array of genes involved in angiogenesis, metabolism, and survival, enabling cancer cells to adapt to and thrive in low-oxygen conditions." (PMID 40563999, 2025). "In pathological contexts such as cancer and ischemia, sustained HIF-1α activity contributes to abnormal or compensatory angiogenesis." (PMID 41150799, 2025). "Among the cancer drivers that show the biggest association changes between CMS2 and CMS4, we found HIF1A and CUX1, both of which are implicated in tumorigenesis and progression, and GATA4, which controls senescence." (PMID 41114645, 2025). "It is thus of great theoretical significance and practical value to explore the role of Chinese herbs in regulating HIF-1α and its application prospects in cancer treatment." (PMID 41585262, 2025). "We and others have shown that P4HA1, an isoform of P4H, enhances the stability of hypoxia-inducible factor-1α (HIF-1α), a vital regulator of the cellular response to hypoxia, which promotes angiogenesis, cancer metastasis, and chemoresistance." (PMID 40694594, 2025). "Functionally, HIF1A drives cancer progression by mediating hypoxia-induced autophagy, epithelial–mesenchymal transition (EMT), and metastasis, positioning it as an oncogenic driver in CCA." (PMID 41300430, 2025). "CPX induces metabolic reprogramming by activating transcription factors such as SOX2, HIF-1α, and c-Myc, thereby reprogramming non-cancer stem cells into cancer stem-like cells." (PMID 41220952, 2025).
cancer (continued). "The downregulation of HIF-1α expression in 2-ANPC-treated cancer cells was due to enhanced proteasome-mediated degradation, whereas the proteasome inhibitor MG-132 effectively reversed this downregulation." (PMID 41514626, 2025). "Within tumors, hypoxic regions arise due to rapid cell proliferation and insufficient vascular supply, compelling cancer cells to adapt through the activation of HIF-1α." (PMID 39981236, 2025). "Nanoparticles have demonstrated the ability to enhance the degradation of HIF-1α, thereby increasing autophagic activity in cancer cells." (PMID 40004215, 2025). "Suppressing the HIF-1α function as a transcription factor is also a promising area in the development of new therapeutic agents, attenuating hypoxia in cancer." (PMID 40710312, 2025). "To further elucidate the link between ER stress and AMPK activation in Liensinine’s effects, we investigated the regulation of HIF-1α, a critical regulator of cancer metabolism." (PMID 40665352, 2025). "The results of KEGG showed that the upregulated genes in high-succinylation subtype were mainly related to HIF-1α signaling and cancer while those in low-succinylation subtype were mainly related to endocytosis, lysosome and autophagy." (PMID 41383634, 2025). "In ovarian cancer, NF-κB, mediated by HIF-1α, induces cancer stem cell characteristics by increasing sirtuin 1 (SIRT1)." (PMID 40420174, 2025). "Under stress conditions like hypoxia, where de novo FA synthesis is compromised, cancer cells compensate by absorbing external lipids, orchestrated by the master regulator HIF‐1α and lipid‐binding proteins like fatty acid‐binding protein 4 (FABP4)." (PMID 39969135, 2025). "Given the central role of WWOX in restraining HIF1α-driven metabolic reprogramming, therapeutic strategies aimed at restoring WWOX function or inhibiting HIF1α activity hold significant potential to disrupt cancer metabolism and improve patient outcomes." (PMID 41007296, 2025). "Zinc supplementation has been shown to counteract the transcriptional repression of HIPK2 induced by hypoxic conditions in cancer cells, leading to a decrease in the expression of HIF-1α." (PMID 39995420, 2025). "The stabilization of HIF-1α has been shown to contribute to chemoresistance and radiosensitization in various cancer types." (PMID 39757165, 2025). "By upregulating molecules involved in glycolysis, such as GLUT1, LDHA and HK2, HIF‐1α enhances glucose uptake and lactate production, providing cancer cells with energy and biosynthetic precursors essential for rapid growth and survival." (PMID 39993964, 2025). "For instance, HIF-1α is a key regulator and plays a key role through signal transduction in the process of cancer angiogenesis, metabolism, invasion, and metastasis." (PMID 39757165, 2025). "Elevated HIF‐1α expression promotes enhanced glycolysis, a critical adaptive mechanism for cancer cells to generate ATP and support survival under these conditions." (PMID 39748215, 2025). "In many cancer cells, nuclear factor-κB (NF-κB) binding sites are present in the promoter of the HIF-1α gene, allowing NF-κB to up-regulate the expression of HIF-1α." (PMID 41585262, 2025). "According to reports, PD-1 pathway promotes cancer cell growth by activating downstream mTOR signaling, which is a master regulator of glucose metabolism by promoting HIF-1α expression." (PMID 40599793, 2025). "Previous studies have indicated that hypoxia-inducible factor-1α (HIF-1α) plays a role in regulating cancer cell glycolysis." (PMID 40519928, 2025). "Second, while the study focused on the interplay between OTUD7B, METTL14, and HIF-1α, it is important to recognize that cancer progression is a multifaceted process involving intricate interactions among multiple genes and factors." (PMID 40746896, 2025). "At the same time, HIF-1α-induced mitophagy enhances aerobic glycolysis, and CAFs secrete high-energy nutrients that can further boost oxidative metabolism in cancer cells." (PMID 41413686, 2025).
cancer (continued). "Among those miRNAs, miR-23a and miR-27a were upregulated by more than 2-fold upon HIF1α P2A OE in cancer cells." (PMID 40701956, 2025). "URP contributes to cancer progression by stabilizing and activating HIF-1α, thereby inducing genes involved in cell proliferation, metabolic adaptation, and angiogenesis." (PMID 40647184, 2025). "This discovery implies that OTUD7B potentially participates in modulating the HIF-1α signaling pathway, a key regulator in the survival, proliferation, and metastatic spread of cancer cells under hypoxic conditions." (PMID 40746896, 2025). "In cancer, HIF‐1α acts as a pivotal factor in shifting cellular metabolism towards glycolysis, even under oxygenated conditions." (PMID 39993964, 2025). "HIF-1α signaling, as the master transcriptional factor of glycolytic metabolism, is frequently activated in human cancers." (PMID 40691138, 2025). "Tsai and co-workers revealed that miR-148a directly inhibits ROCK1 and c-Met, leading to the downregulation of HIF-1α, a key factor in hypoxia-induced cancer progression." (PMID 40871106, 2025). "More and more studies have shown that overexpression of HIF1α exists in cancer cells even under normoxic conditions." (PMID 40469197, 2025). "In conclusion, the present study demonstrates that dauricine significantly enhances the antitumor effects of sorafenib in NSCLC known as non-small cell lung cancer by modulating key cancer signaling pathways, particularly those mediated by HIF-1α." (PMID 40205002, 2025). "Iron chelation is pivotal in increasing HIF-1α expression for antitumor immune responses as shown here and also by inhibiting the progression of cancer cell malignancy." (PMID 40343532, 2025). "Overall, HIF-1α-mediated fructose production supports glycolytic ATP generation under low oxygen, promoting cancer cell viability despite impaired oxidative phosphorylation." (PMID 40520908, 2025). "Like cancer, colitis is characterized by an upregulation in both hypoxia-inducible factor (HIF-1α) and NF-κB." (PMID 40599807, 2025). "Hypoxic conditions prevalent in cancers activate pathways like hypoxia-inducing factor 1α (HIF-1α), which promote CSCs' survival and proliferation." (PMID 40821110, 2025). "The effective enhancement of radiosensitivity through PI3K/mTOR pathway inhibition and HIF1‐α knockdown highlights the potential of targeting these pathways to overcome radioresistance in cancer treatment." (PMID 40740483, 2025). "The upregulation of GLUT1, GLUT3, and GLUT4 is mediated by insulin and HIF-1α, and is correlated with drug resistance in cancers." (PMID 40612109, 2025). "Hypoxia-inducible factor-1α (HIF-1α) is a pivotal regulatory factor in adapting to hypoxic conditions, and numerous genes have been identified as direct transcriptional targets of HIF-1α in CAFs or cancer cells." (PMID 40185722, 2025). "While several HIF subtypes participate in hypoxic regulation in different ways, the function of HIF-1α, as a key mediator of angiogenesis, has been widely studied and used as a target molecule for cancer therapies." (PMID 40430033, 2025). "Overall, this research introduces new plant-derived compounds aimed at improving cancer treatment by disrupting the interaction between p300 and HIF1α." (PMID 40284037, 2025). "Strategies including small molecule inhibitors and nanoparticle-mediated delivery of drugs possess the potential to reduce HIF-1α activity, hence reducing cancer progression while protecting fertility." (PMID 40136686, 2025). "By advancing our understanding of HIF-1α-driven processes and leveraging emerging technologies, researchers and clinicians can unlock new opportunities to improve cancer immunotherapy outcomes and patient survival." (PMID 39981236, 2025). "HIF-1α is widely recognised as a key regulator of angiogenesis, metabolic reprogramming, and immune evasion in cancer." (PMID 41463127, 2025). "Research indicates that AuNPs can decrease HIF-1α expression, facilitating autophagic degradation in cancer cells." (PMID 40004215, 2025).
cancer (continued). "This was linked with increased HIF1a protein nuclear localization, indicative of hypoxia, and the highest protein expression of the glycolytic marker GLUT1 in cancer cells." (PMID 40482194, 2025). "Recent studies have shown that activation of signal transducer and activator of transcription 3 (STAT3) and HIF-1α in innate immune B cells stimulated by lipopolysaccharide (LPS) can exacerbate cancer metastasis." (PMID 40430040, 2025). "Fibroblast S8 cells exhibited high expression of HIF1A and VEGFA, suggesting similarity to hypoxia‐associated cancer‐associated fibroblasts (CAFs)." (PMID 40432877, 2025). "Since the HIF1α transcription factor is a main factor for cancer metabolic adaptation, WWOX regulation of HIF1 is particularly relevant." (PMID 41007296, 2025). "Hypoxia within the TME critically influences the progression of cancer by modulating tumor suppressor genes, primarily via the stabilization of hypoxia-inducible factors (HIFs) such as HIF-1α and HIF-2α." (PMID 39911323, 2025). "After a 48-h incubation under either normoxic or hypoxic conditions, HIF-1α levels were detected via western blot analysis to assess the successful induction of hypoxic stress in the cancer cells." (PMID 40148311, 2025). "The resultant phospholipid‐rich microenvironment activates an HSP90/HIF1A signaling axis in malignant epithelial cells, fueling cancer stemness and therapeutic escape." (PMID 40917018, 2025). "Given its central role in modulating the cellular response to hypoxia, HIF-1α has emerged as a crucial target in cancer therapy." (PMID 41311849, 2025). "Hypoxic cancer cell survival is mediated by the overexpression of the anti-apoptotic Bcl-2 family member Mcl-1 in solid tumors, which is regulated by HIF-1α and correlates to poor survival." (PMID 40963621, 2025). "Agents targeting VEGF, a major downstream effector of HIF-1α, have been clinically validated in cancer therapy." (PMID 39981236, 2025). "PKM2 is a downstream molecule of hypoxia-inducible factor 1α (HIF-1α) and a key enzyme involved in aerobic glycolysis of cancer cells." (PMID 41272362, 2025). "HIF-1α is a master regulator of how cancer cells respond to hypoxia and is crucial for cancer cell survival as it activates the transcription of genes involved in resistance to radiation therapy, chemotherapy, and angiogenesis." (PMID 40214422, 2025). "This suppression leads to the accumulation of HIF-1α in endothelial cells, thereby enhancing angiogenesis under both normoxic and hypoxic conditions, and increasing vascular permeability and cancer transendothelial migration." (PMID 41573685, 2025). "In the case of tirapazamine, bioreduction leads to apoptosis and HIF-1α downregulation in cancer cells." (PMID 40867888, 2025). "WSB1, an E3 ligase component, promotes hypoxia-inducible factor 1α (HIF-1α) degradation under normoxia, which promotes cancer invasion and metastasis." (PMID 40375984, 2025). "HIF-1α also upregulates IAPs, helps to maintain cancer stem cells, and regulates autophagy, thereby enhancing cell viability and resistance in lung tumors." (PMID 41007213, 2025). "Key features of cancer metabolism - such as increased glucose uptake, reduced respiration, and lactate production - are heavily influenced by HIF-1α." (PMID 40546546, 2025). "These processes promoted the transcription of HIF1A, contributing to cancer progression and metastasis." (PMID 40102715, 2025). "The AMPK pathway is a known regulator of cancer growth and progression, inhibiting several other pro-cancer pathways including mToR, HIF-1α, β-catenin, and Yap-1." (PMID 39941833, 2025). "ROS is crucial for regulating angiogenesis, which is important for cancer spread; it induces HIF-1α expression and stabilizes it, increasing VEGF and promoting angiogenesis." (PMID 40497987, 2025). "This study highlights the critical role of HIF-1α in modifying histone enzymes under hypoxic conditions, thereby contributing to the dynamic regulation of gene expression in cancer cells." (PMID 39911323, 2025).